ALB (albumin)
Diseases named in the same sentence as ALB in open-access papers (continued):
Sharing a sentence is not in itself a finding about the gene and the disease.
glioblastoma (continued). "Moreover, the mechanism by which serum albumin levels can predict the prognosis of glioblastoma patients should be further explored." (PMID 25880463, 2015). "Preoperative serum albumin levels have been recognized as prognostic in glioblastomas." (PMID 25880463, 2015). "A relationship between serum albumin and survival in glioblastoma patients has also been reported." (PMID 25880463, 2015). "Albumin has been reported to naturally accumulate in various types of solid tumors, including sarcomas, lung cancers, and glioblastoma multiforme (GBM)." (PMID 39904854, 2025). "In the study, the imaging of glioblastoma (GBM) cell lines and human clinical GBM tissues was successfully demonstrated, and the study presented great promise for the application of these albumin complexes for GBM identification and surgery at clinical sites." (PMID 38323081, 2024). "Therefore, during glioblastoma-induced inflammatory responses, the interaction among albumin, IGFBP-2 and IL-6 may greatly affect clinical outcomes." (PMID 25880463, 2015). "Moreover, the permeability of BBB may be greater among glioblastoma patients with low serum albumin levels." (PMID 25880463, 2015). "The ongoing phase II portion is investigating the use of focused ultrasound to deliver both albumin-bound paclitaxel and carboplatin in conjunction with LIPU-MB in patients with recurrent glioblastoma." (PMID 39451851, 2024). "Other types of polymeric NPs have also been tested, including a NP based on serum albumin, which was shown to be capable of carrying siRNA targeting STAT3, a transcription factor involved in glioblastoma progression, thereby improving survival in mouse models." (PMID 35456971, 2022). ", who verified the influence of IONPs coated with bovine serum albumin (BSA) as well as BSA‐coated and PEGylated on primary human fibroblasts and U251 human glioblastoma cell line." (PMID 32963318, 2020). "Hsp70-specific antibody (cmHsp70.1) and survivin-targeting miRNA plasmid-loaded human serum albumin (HSA) NPs (180 nm–220 nm) significantly reduced survivin expression and enhanced caspase 3/7 activity in U87 MG and LN229 glioblastoma cells under irradiation." (PMID 32168899, 2020). "For example, doxorubicin, paclitaxel, or albumin-paclitaxel (Abraxane) has shown interesting effects in pre-clinical models of glioblastoma, but the lack of BBB passage impedes reaching a sufficient therapeutic concentration at the tumor site." (PMID 38791053, 2024). "Proof-of-concept of 18F-labeling with heat/solvent-sensitive biomolecules in one step is demonstrated by biomolecular tracers include 18F-labeled human serum albumin (HSA) for blood pool imaging and 18F-labeled c(RGDyk) which targets the integrin αvβ3 receptor of the U87MG cell (glioblastoma)." (PMID 30824691, 2019). "In the present study, we found that preoperative serum albumin levels significantly correlated with survival in glioblastoma patients who received no or incomplete adjuvant treatment." (PMID 25880463, 2015). "Although CSF albumin levels in brain cancers such as MB and glioblastoma have not been directly measured, mass spectrometry data supports slightly increased albumin levels in glioblastoma." (PMID 37213306, 2023). "This study successfully demonstrates the development and optimization of a novel bovine serum albumin (BSA) nanoparticle (NP) platform designed for the synchronized delivery of all-trans retinoic acid (ATRA) and curcumin (CURC) to combat glioblastoma (GBM)." (PMID 41598285, 2026). "Furthermore, a negative correlation was observed between tumor volume and albumin levels, suggesting that larger tumor volumes may reflect heightened systemic inflammation in glioblastoma patients." (PMID 40283046, 2025).
IgA nephropathy (45 papers, 2006 to 2026). "Low serum albumin is a risk factor for adverse IgA nephropathy outcomes." (PMID 39492771, 2025). "Remarkably, oxidative stress on mesangial cells has been shown to be a key pathogenic factor in the onset and progression of IgA nephropathy, thus suggesting that the protective action of serum ALB in this context mostly relies on its massive antioxidant capability." (PMID 37762957, 2023). "Endothelin 1 correlated with albumin in membranous nephropathy, total protein, albumin, creatinine in FSGS, total protein in IgA nephropathy, total protein, and albumin in CKD." (PMID 41517469, 2025). "In exposing the glomerular endothelial cells to 0.5% serum from patients suffering from IgA nephropathy, MN, minimal change disease, and lupus nephritis (five patients for each disease), they assessed podocyte viability and the albumin permeability after 24 h." (PMID 40621859, 2025). "Their results showed significant reduction in podocyte viability for the majority of the conditions, while the albumin permeability was significantly increased for three MN's sera and one IgA nephropathy's serum." (PMID 40621859, 2025). "In conditions with nephrotic range proteinuria, serum albumin of >3.5 gm/dl can predict IgA nephropathy with a specificity of 95.8%." (PMID 39618658, 2024). "Albumin permeability was increased in most models of serum-induced IgA nephropathy (IgAN) and membranous nephropathy (MN)." (PMID 38791159, 2024). "Albumin filtered through diseased glomeruli accounts for the majority (60–70%) of urinary protein composition in IgA nephropathy." (PMID 39767752, 2024). "Immunosuppressive therapy for severe IgA nephropathy can effectively reduce urinary protein levels, increase serum albumin levels, and protect renal function in the early stage of treatment." (PMID 36998610, 2023). "Another trial, which included the administration of calcitriol using 0.5 μg two times a week for a length of 12 consecutive years, in 10 patients resulted in a major reduction of the urine albumin to creatinine ratio, proved by IgA nephropathy." (PMID 36984797, 2023). "Albumin level in the membranous nephropathy group was lower in comparison with IgA nephropathy, lupus nephritis, c-ANCA, and p-ANCA vasculitis groups." (PMID 36152104, 2022). "The animal model of IgA nephropathy was established by bovine serum albumin (BSA) + lipopolysaccharide (LPS) + carbon tetrachloride (CCL4) in 22 studies, and BSA + staphylococcal enterotoxin-B (SEB) in 8 studies." (PMID 36601331, 2022). "Albumin level in the focal and segmental glomerulosclerosis group was lower compared to IgA nephropathy, c-ANCA, and p-ANCA vasculitis groups." (PMID 36152104, 2022). "Albumin level in the IgA nephropathy group was higher compared to membranous nephropathy and focal and segmental glomerulosclerosis groups." (PMID 36152104, 2022). "We collected clinical data, including age, sex, serum urea nitrogen, serum uric acid, urinary 24 h total protein, HB, serum albumin, serum creatinine, and eGFR, from IgA nephropathy patients." (PMID 35173546, 2022). "These nine variables were age, sex, DBP, ALB, CHOL, TG, CKD stage, M, and T, which were associated with IgA nephropathy complicated by renal anaemia." (PMID 34013043, 2021). "In this sense, the plasma measurement of free albumin–Cys34 has been used as an oxidative stress marker, which is decreased in patients with IgA nephropathy." (PMID 33800425, 2021). "Specifically, loci were identified with urate/urea/uric acid levels (KLHDC7A,36MTX1,37RREB1,38 and MIR153828,38), urine albumin-to-creatinine ratio (C9orf339), IgA Nephropathy (MTMR340), and frequency of urinary tract infection (ZNF16541)." (PMID 31451708, 2019). "In accordance with previous studies on IgA nephropathy, proteinuria (HR, 1.89; p < 0.001), age (HR, 1.060; p = 0.023), serum albumin (HR, 0.31; p = 0.002) and serum cholesterol (HR, 1.02; p = 0.007) were also significantly associated with deterioration of renal function." (PMID 39767752, 2024).
IgA nephropathy (continued). "Urinary albumin is a well-known predictor of progression of IgA nephropathy." (PMID 39767752, 2024). "Univariate logistic regression analysis showed that MAP, proteinuria, urine osmolality, blood albumin, baseline serum creatinine, blood uric acid, cystatin C, and baseline eGFR were predictive indicators of tubular atrophy/interstitial fibrosis in IgA nephropathy." (PMID 38426107, 2024). "Five SNPs used for genetic prediction of PCa, 1 for IgA nephropathy, 4 for urinary albumin excretion, 1 for potassium in urine, 3 for sodium creatine in urine, 2 for serum creatinine (eGFRcrea), and 1 for serum cystatin C (eGFRcys) were excluded due to the presence of confounding factors.." (PMID 38348104, 2024). "• Decreases urinary albumin/creatinine ratios in IgA nephropathy patients." (PMID 36860293, 2023). "In IgA nephropathy group, serum total protein and albumin levels were lower than those of the control group, but 24 h urine protein, complement C4, serum IgA, cholesterol, and triglycerides in IgA nephropathy group were significantly increased versus the control group (data not shown)." (PMID 28270699, 2017). "However, in the present study, the serum albumin levels of patients with MN and IgA nephropathy were similar." (PMID 24707402, 2014). "Compared with primary IgA nephropathy, IgA-dominant postinfectious glomerulonephritis had more proteinuria and lower serum albumin level, indicating that it had greater damage on glomerular filtration barrier, which may be one of the reasons for more serious disease progression." (PMID 34225678, 2021). "PAR 1 correlated with total protein, albumin in SLE, total protein in IgA nephropathy, and creatinine in CKD." (PMID 41517469, 2025). "In a study involving two patients with IgA nephropathy, intensive fresh FMT over 6–7 months led to partial clinical remission, with significant reductions in urinary protein levels, increased serum albumin, and stable kidney function." (PMID 40559778, 2025). "Prospective analysis of albumin levels showed increasing levels of albumin during time among patients with higher AT1R antibodies levels in lupus nephritis, IgA nephropathy, c-ANCA and p-ANCA vasculitis." (PMID 36152104, 2022). "In recent years, attention has been focused on the oxidation state of albumin in various pathologies, since an increase in oxidized proteins has been observed in patients with CKD and IgA nephropathy, among other kidney pathologies." (PMID 33800425, 2021). "The objective of this study was to investigate whether the albumin-to-fibrinogen ratio (AFR) can predict corticosteroid response and prognosis prediction among IgA nephropathy (IgAN) patients." (PMID 37013663, 2023). "The results also showed that the application of YQH method did not increase the serum level of ALT, nor does it decrease the serum level of Hb and ALB, which means that the method did not have an adverse effect on patients with IgA nephropathy." (PMID 36897707, 2023). "This study supports the recommendation of using the albumin-to-creatinine ratio, rather than 24-hour proteinuria, to monitor proteinuria and prognosis in primary IgA nephropathy." (PMID 27276392, 2016). "Anti-PAR 1 and anti-ACE 2 correlated negatively with total protein and albumin levels in LN and were higher in LN than in membranous nephropathy, FSGS, IgA nephropathy, non-IgA mesangial proliferative glomerulonephritis, and c-ANCA-positive vasculitis." (PMID 40364208, 2025). "This study found good clinical efficacy of the YQH method in patients with IgA nephropathy, it can reduce 24hPRO and SCr without impact the normal level of ALT Hb and serum albumin." (PMID 36897707, 2023).
multiple myeloma (45 papers, 2013 to 2026). "The reason for decreased albumin synthesis, in this case, can be attributed to the hepatic involvement from the AL amyloidosis." (PMID 39131015, 2024). "Renal function is often compromised in AL-amyloidosis; therefore, renal function, creatinine and serum-albumin levels should be assessed including urinalysis to indicate and specify proteinuria." (PMID 38809394, 2024). "For protein dyscrasias and particularly for AL amyloidosis, the disease state and the % albumin in the urine can vary widely, so calculating the amount of non-albumin protein was necessary for each sample in our study." (PMID 36267963, 2022). "Renal dysfunction in AL amyloidosis patients results in proteinuria, consisting mostly of albumin and immunoglobulin molecules." (PMID 36267963, 2022). "We retrospectively reviewed 575 patients with systemic AL amyloidosis to assess the correlation between a urine albumin to creatinine ratio (uACR) and the 24hUP." (PMID 33311451, 2020). "As these amyloid proteins were positive for p-component staining and negative for amyloid A staining, β2-microglobulin, and pre-albumin, we diagnosed the patient with AL amyloidosis." (PMID 33639890, 2021). "As these amyloid proteins were positive for p-component staining and negative for amyloid A staining, β2-microglobulin, and pre-albumin, and as lambda light chains were positive in the mesangial region, we diagnosed the patient with MGRS-related AL amyloidosis." (PMID 33639890, 2021).
protein-energy malnutrition (45 papers, 2005 to 2025). A nutritional deficit that is caused by inadequate protein or calorie intake. "Additionally, albumin (p = 0.1) and total protein (p = 0.2) levels tended to show more depletion in TG patients, reinforcing the known risk of protein-energy malnutrition following total gastric resection." (PMID 40647250, 2025). "The finding may be associated with protein energy malnutrition that leads to a decrease in albumin and BMI of VL patients." (PMID 34797863, 2021). "In addition, serum albumin level is one of the biochemical markers of nutritional status and it has been reported that protein-energy malnutrition after acute stroke is a risk factor for poor outcome worsening the prognosis." (PMID 23110752, 2012). "Decreased hepatic synthesis of albumin and fibrinogen, along with increased muscle proteolysis via the ubiquitin–proteasome system, contributes to progressive protein-energy malnutrition." (PMID 41228421, 2025). "The liver synthesizes serum albumin and it is often used as a marker to assess nutritional status, particularly protein-energy malnutrition." (PMID 40370727, 2025). "Severe protein energy malnutrition, presented as low albumin levels, were also only observed in patients with a CC ≤ 250 cm (4–12%)." (PMID 40343655, 2025). "Simultaneously, the ongoing demand for BCAAs to support residual glutamine synthesis further depletes these essential amino acids, compounding protein-energy malnutrition and impairing albumin synthesis." (PMID 41228421, 2025). "Serum albumin levels have been identified to directly reflect nutritional status, and protein-energy malnutrition has been found to be common in MHD patients, with prevalence rates ranging from 23 to 73%." (PMID 37542595, 2024). "Serum albumin, a widely accepted indicator of nutritional status, indicates protein-energy malnutrition resulting from the stress of illness, injury, or infection." (PMID 39416435, 2024). "The use of albumin levels to infer protein energy malnutrition was previously commonplace in clinical practise." (PMID 36891188, 2023). "Cirrhotic patients suffer from protein-energy malnutrition, characterized by accelerated gluconeogenesis, proteolysis and lipolysis, resulting in the depletion of albumin, adipose tissue and muscle mass." (PMID 36765884, 2023). "Traditionally, albumin and pre-albumin values were biochemical tests considered useful for the assessment of patients’ nutritional status, with low levels indicating protein-energy malnutrition." (PMID 36233551, 2022). "However, If a child has a poorly balanced diet, deficiencies in calcium, iron, albumin, vitamin D, and protein-energy malnutrition may induce enamel hypoplasia/hypomineralization, roughening the enamel surface and prone to plaque accumulation, with can lead to post-eruptive caries." (PMID 36568786, 2022). "Nutritional evaluation: The mean serum albumin was 29.2 ± 4.8 g/L, and 143 patients (48.8%) were found to have severe protein-energy malnutrition." (PMID 32599756, 2020). "Serum albumin is universally accepted to be a better index for protein-energy malnutrition than anthropomorphic markers." (PMID 28570652, 2017). "While CONUT incorporates immune (lymphocyte count) and lipid (total cholesterol) parameters, both potentially influenced by statins, GNRI, NRI, and PNI primarily rely on serum albumin and anthropometric measures, thereby better reflecting protein-energy malnutrition and frailty." (PMID 40984946, 2025). "Serum albumin and prealbumin are indicators that reflect protein-energy malnutrition." (PMID 40959701, 2025). "On the other hand, serum albumin could somewhat reflect nutrient status and protein-energy malnutrition after AIS was deleterious to the prognosis of patients with AIS." (PMID 38918991, 2024). "Albumin is a good indicator of protein-energy malnutrition in CKD." (PMID 33256618, 2020).
protein-energy malnutrition (continued). "Recently, the American Society for Parenteral and Enteral Nutrition published a statement recognizing albumin and prealbumin as important factors that correlate the risk for adverse outcomes in patients, but should not be used for diagnosing protein-energy malnutrition." (PMID 35158762, 2022). "As it is well known that serum albumin, serum creatinine, BMI, body fat mass, and SGA are good surrogate markers of protein-energy wasting, a PD patient developing protein-energy malnutrition may gradually acquire ECW accumulation to balance loss of body cell mass or fat mass." (PMID 23341936, 2013). "They found that the traditional methods (weight-for-height, loss of weight and albumin) for assessing protein energy malnutrition did not detect more than two-thirds of the patients with reduced muscle protein mass, as indicated by muscle thickness ultrasonography." (PMID 16444387, 2005). "Importantly, the American Society for Parenteral and Enteral Nutrition recognized albumin and prealbumin as important factors that correlate with the risk for adverse outcomes in patients, though they should not be used for diagnosing protein-energy malnutrition." (PMID 35008278, 2021). "Patients with a serum albumin less than 3.5 grams/dL and/or a TLC less than 1,500 cells per mm3 were classified as having protein energy malnutrition." (PMID 26339558, 2015). "Recent studies suggest that albumin characterizes inflammatory processes rather than nutritional status or protein-energy malnutrition." (PMID 39618077, 2024). "The reason for this superiority of albumin is that it reflects protein energy malnutrition unlike cBMI, which simply reflects the nutritional status of patients." (PMID 29545522, 2018). "According to the ASPEN position paper, albumin and prealbumin should not be used as sole proxies for nutritional status because their levels decline in the presence of inflammation irrespective of true protein-energy malnutrition." (PMID 41156511, 2025).